CCDC136 (coiled-coil domain containing 136)
Description:
May play a role in acrosome formation in spermatogenesis and in fertilization.
Synonyms: KIAA1793; NAG6; DKFZP434G156
Tractability: Antibody: UniProt predicts a signal peptide or a membrane-spanning region; the Human Protein Atlas places it where antibodies can reach. PROTAC: ubiquitination databases record sites on it; its protein half-life has been measured.
Gene: Protein-coding gene on chromosome 7 (128,790,757 to 128,822,135, forward strand). Ensembl gene ENSG00000128596.
Subcellular location: Cytoplasmic vesicle, secretory vesicle, acrosome membrane
Subcellular location (Human Protein Atlas): Plasma membrane; Golgi apparatus; Mid piece; Vesicles
Gene Ontology:
Biological process: acrosome assembly; single fertilization; spermatogenesis
Cellular component: acrosomal membrane
Genetic constraint (gnomAD): Loss-of-function variants: 94 observed, 120.8 expected, observed/expected ratio (o/e) 0.78, 90% interval 0.66 to 0.92. The upper end of that interval is the gene's LOEUF score, 0.92, which puts it in group 3 of 6, group 1 being the genes least tolerant of losing a copy. Missense variants: 1,193 observed, 1,309.3 expected, observed/expected ratio (o/e) 0.91, 90% interval 0.87 to 0.96. Synonymous variants: 469 observed, 493.86 expected, observed/expected ratio (o/e) 0.95, 90% interval 0.88 to 1.02.
Homologues: Orthologues: chimpanzee CCDC136 (98% identical), macaque CCDC136 (95% identical), dog CCDC136 (76% identical), guinea pig CCDC136 (72% identical), rabbit CCDC136 (72% identical), rat Ccdc136 (70% identical), mouse Ccdc136 (70% identical), pig CCDC136 (69% identical), tropical clawed frog ccdc136 (14% identical), zebrafish ccdc136b (12% identical), zebrafish ccdc136a (12% identical), Drosophila melanogaster Slmap (4% identical), and 1 more. Paralogues in human: SLMAP (11% identical), TRAF3IP3 (5% identical).
Diseases named in the same sentence as CCDC136 in open-access papers:
CCDC136 is named in the same sentence as 12 diseases in open-access papers, as found by Europe PMC text mining. Sharing a sentence is not in itself a finding about the gene and the disease. The quoted sentences say what the papers report.
gastric cancer (2 papers, 2014 to 2017). A primary or metastatic malignant neoplasm involving the stomach. "CCDC136 (also known as NAG6) is a coiled-coil domain containing protein described as a potential tumor suppressor in gastric cancer." (PMID 28866788, 2017).
male infertility (2 papers, 2023 to 2025). The inability of the male to effect fertilization of an ovum after a specified period of unprotected intercourse. "In CCDC136 knockout mice, the disruption of acrosome morphology and the associated male infertility underscore the importance of this protein’s role in both structural and functional aspects of spermatogenesis." (PMID 40407495, 2025). "Knockout of Ccdc9, Ccdc38, Ccdc42, Ccdc62, Ccdc87 and Ccdc136 results in male infertility in mouse models because of defects in sperm flagella." (PMID 37601242, 2023).
breast carcinoma (1 paper, 2023). "Only three variants were observed not only in the affected cousin pair, but also in the other recurrent breast cancer cases sequenced in the same pedigree (in genes TENM2, CCDC136, and MDH2)." (PMID 38136396, 2023).
dementia (1 paper, 2020). Loss of intellectual abilities interfering with an individual's social and occupational functions. "Valproic acid was identified as a potential therapeutic agent that may regulate the mutual switch genes shared among the dementias (PDE4DIP, NEAT1, LPIN3, ADCYAP1, CCDC136, and ITPKB)." (PMID 32471155, 2020).
Infertility (1 paper, 2025). "Knockout studies in mice have shown that the absence of CCDC136 results in severe acrosome defects, leading to infertility." (PMID 40276155, 2025).
cancer (2 papers, 2016 to 2020). A tumor composed of atypical neoplastic, often pleomorphic cells that invade other tissues. "We describe the development of a novel GFP-reporter mouse line with a gene trap insertion into the Coiled-coil domain containing 136 (Ccdc136)/nasopharyngeal carcinoma-associated gene 6 (NAG6) locus." (PMID 26965927, 2016). "Six pDGVs in the PINX1, MOB1A, CLTCL1, PRR5, CCDC136, and TRIM32 genes involved the exact amino acid residues affected by known somatic cancer variants." (PMID 33273457, 2020).
CCDC136 also shares sentences with these, for which no sentence is quoted: tumor (2 papers); autoimmune (1); coronary heart disease (1); hypertrophic cardiomyopathies (1); pancreatic cancer (1); retinal degeneration (1).